VAX1 (ventral anterior homeobox 1)
Description:
Transcription factor that may function in dorsoventral specification of the forebrain. Required for axon guidance and major tract formation in the developing forebrain. May contribute to the differentiation of the neuroretina, pigmented epithelium and optic stalk (By similarity).
Synonyms: MCOPS11
Tractability: No criterion of Open Targets' tractability assessment is met for any kind of drug.
Gene: Protein-coding gene on chromosome 10 (117,128,521 to 117,138,301, reverse strand). Ensembl gene ENSG00000148704.
Subcellular location: Nucleus
Subcellular location (Human Protein Atlas): Nucleoli rim; Nucleoplasm
Gene Ontology:
Molecular function: sequence-specific double-stranded DNA binding; DNA-binding transcription factor activity, RNA polymerase II-specific; RNA polymerase II cis-regulatory region sequence-specific DNA binding; chromatin DNA binding; DNA binding; DNA-binding transcription factor activity; DNA-binding transcription repressor activity, RNA polymerase II-specific; RNA polymerase II intronic transcription regulatory region sequence-specific DNA binding
Biological process: brain development; central nervous system development; neuron differentiation; regulation of transcription by RNA polymerase II; negative regulation of transcription by RNA polymerase II; regulation of DNA-templated transcription
Cellular component: chromatin; nucleus
Genetic constraint (gnomAD): Loss-of-function variants: 6 observed, 17.47 expected, observed/expected ratio (o/e) 0.34, 90% interval 0.19 to 0.68. The synonymous counts are far from expectation, so gnomAD's model fits this gene poorly and the ratio says little. Missense variants: 408 observed, 419.75 expected, observed/expected ratio (o/e) 0.97, 90% interval 0.9 to 1.05. Synonymous variants: 256 observed, 204.36 expected, observed/expected ratio (o/e) 1.25, 90% interval 1.13 to 1.39.
Homologues: Orthologues: chimpanzee VAX1 (99% identical), dog VAX1 (99% identical), macaque VAX1 (99% identical), pig VAX1 (98% identical), rat Vax1 (97% identical), mouse Vax1 (96% identical), guinea pig VAX1 (86% identical), rabbit VAX1 (77% identical), zebrafish vax1 (69% identical), tropical clawed frog vax1 (65% identical), Drosophila melanogaster lms (27% identical). Paralogues in human: VAX2 (43% identical), EMX1 (18% identical), EMX2 (16% identical).
Diseases named in the same sentence as VAX1 in open-access papers:
VAX1 is named in the same sentence as 23 diseases in open-access papers, as found by Europe PMC text mining. Sharing a sentence is not in itself a finding about the gene and the disease. The quoted sentences say what the papers report.
coloboma (12 papers, 2007 to 2023). An abnormality in which a part of a structure in one or both eyes is missing. "Our cross-species meta-analysis also provided evidence that genes previously associated with coloboma causation in model organisms, such as VAX1, NTN1, and NID1, should be more widely recognised as possible human MAC candidates." (PMID 36830662, 2023). "Coloboma, the fissures in the ventral eyecup and OS, is observed in the eyes of humans and mice harboring VAX1 mutations." (PMID 36737666, 2023). "Both in this patient and in the Vax2-null mouse, the phenotype is mild compared to that associated both with a previously reported human VAX1 mutation and a targeted murine Vax1 deletion, where coloboma was fully penetrant and moderately severe." (PMID 26068435, 2015). "The correct patterning of the optic fissure is dependent on the actions of Bmp7 and Shh and mutations in Pax2 and Vax1 lead to a deficiency in the closure of the optic fissure, a condition known as coloboma." (PMID 20386732, 2010). "Genetic inactivation of Vax1 in humans and mice causes agenesis of multiple midline structures of the brain, including the anterior commissure, the corpus callosum, and the OC, in addition to the coloboma of the eye." (PMID 25201875, 2014). "In Danio rerio, injection of antisense morpholinos against Vax1 resulted in colobomas and reduced retinal pigment at the site of the choroid fissure." (PMID 32111086, 2020). "Injections of antisense morpholinos against Vax2 or Vax1 resulted in colobomas and reduced retinal pigment at the site of the choroid fissure in Danio rerio." (PMID 32111086, 2020). "Colobomas were rare and milder in Vax2 homozygous null mutants, but Vax1 and Vax2 double-mutant mice had severe colobomas that were fully penetrant." (PMID 32111086, 2020). "These included the known human coloboma associated genes (indicated by #): SMOC1, PAX2, VAX1 and ALDH6, in addition to the coloboma candidates from other animal studies CHRDL1 and CYP1B1 (indicated by •)." (PMID 31162046, 2019). "This mutation was reported in a human patient who exhibited coloboma, cleft palate, and agenesis of corpus callosum (ACC), phenotypic manifestations similar to those of Vax1−/− mice." (PMID 25201875, 2014). "VAX1 has been also identified as a candidate gene playing a role in human nonsyndromic cleft lip with or without cleft palate, which can be accompanied by brain anomalies, eye coloboma, and syndromic microphthalmia." (PMID 32111086, 2020). "We found that depletion of kdm5c significantly downregulated vax1, vax2, pax6 expressions, while tbx5 expression was slightly reduced; thus, the reduced expression of DV-patterning markers may be responsible for the colobomas observed in kdm5c morphants." (PMID 30522514, 2018). "Among these were the known human MAC genes TENM3, SMOC1, PAX2, ALDH1A3, and BMPR1B, in addition to NID1, VAX1, and NTN1, which have been previously identified as MAC or coloboma candidates based on animal studies." (PMID 36830662, 2023).
microphthalmia (8 papers, 2012 to 2023). Congenital or developmental anomaly in which the eyeballs are abnormally small. "From studies of 70 patients, a report found associations of two homozygous mutations in VAX1 with microphthalmia, cleft lip and palate, and agenesis of the corpus callosum." (PMID 32475352, 2020). "Microphthalmia associated with cleft lip and palate and agenesis of the corpus callosum caused by homozygous mutation in the Vax1 gene was reported." (PMID 32111086, 2020). "A study implicated two homozygous mutations in VAX1 causing microphthalmia associated with cleft lip and palate and agenesis of the corpus callosum." (PMID 32475352, 2020). "Ultimately, consistent with its role as a SHH signaling mediator and similar to the mouse mutant phenotype, a human VAX1 mutation has been found in a patient with microphthalmia in association with cleft lip/palate." (PMID 30073412, 2019). "A single case has been reported wherein a mutation in VAX1 (R152S) was found in a patient with microphthalmia, optic nerve hypoplasia, cleft lip/palate and corpus callosum agenesis, a phenotype similar to that found in the Vax1 null mouse." (PMID 26068435, 2015). "Gli3 knockout mutants develop microphthalmia, with reduction in the Pax6-expressing distal domain of the optic vesicle, and concomitant upregulation of Pax2 and Vax1/2 TFs in the stalk, which thickens." (PMID 30073412, 2019). "Interestingly, genes involved in microphthalmia (VAX1, ALDH1A3, GJA1, and SMOC1) and retinal dystrophies (ADAMTS9, KCNJ13, CA2 and ABCA4) were also selected." (PMID 37479765, 2023).
cleft lip (4 papers, 2013 to 2024). Congenital defect in the upper lip where the maxillary prominence fails to merge with the merged medial nasal prominences. "Genome-wide association studies reported the rs7078160 of Vax1 is closely related to non-syndromic cleft lip with or without cleft palate in European populations." (PMID 33132092, 2021). "This study suggests that rs7078160 polymorphism is a risk factor of non-syndromic cleft lip with or without cleft palate, and Vax1 is strongly associated with non-syndromic cleft lip with or without cleft palate in Southern Chinese Han populations." (PMID 33132092, 2021).
cleft palate (4 papers, 2013 to 2021). Cleft palate is a fissure type embryopathy that affects the soft and hard palate to varying degrees. "VAX1 knock-out mice have been shown to develop cleft palate, suggesting VAX1 has a potentially important role in nsCL/P etiology." (PMID 30638414, 2019). "Vax1-null mice undergo neonatal mortality due to severe holoprosencephaly and cleft palate." (PMID 32111086, 2020).
bladder cancer (3 papers, 2021 to 2025). "VAX1 is associated with bladder cancer recurrence, and a combination of 8 genes, including VAX1, can be used as a diagnostic marker for monitoring bladder cancer disease progression." (PMID 41262242, 2025). "Remarkably, VAX1 and LMX1A methylation were more frequently detected in urine samples from recurrent bladder cancer patients as compared to that of newly diagnosed bladder cancer patients, thus suggesting that the methylation of VAX1 and LMX1A was associated with bladder cancer recurrence." (PMID 37627900, 2023). "One study had shown that VAX1 was closely related to bladder cancer recurrence." (PMID 33941222, 2021). "A 5-gene panel (VAX1, CFTR, KCNV1, PROX1, and TAL1) had an 88.7% sensitivity and an 87.3% specificity for the diagnosis of bladder cancer." (PMID 37627900, 2023). "The methylation frequency of eight genes (VAX1, ECEL1, KCNV1, LMX1A, PROX1, SLC6A20, TAL1, and TMEM26) was significantly higher in the urine of bladder cancer patients as compared to that of normal controls." (PMID 37627900, 2023).
orofacial cleft (3 papers, 2016 to 2025). A disorder of facial skeleton that is characterized by cleft lip and/or cleft palate that result in feeding, speech and hearing problems caused by failures during development. "Our study identified a significant association between the VAX1 rs7078160 variant and NSCL/P risk in a Japanese population, supporting its role as a susceptibility locus for orofacial clefting." (PMID 40869910, 2025).
Infertility (2 papers, 2016). "This study identifies VAX1 as a key transcription factor regulating GnRH expression and establishes VAX1 as a novel candidate gene implicated in heritable infertility." (PMID 28164172, 2016). "Absence of Vax1 from GnRH neurons abolishes GnRH expression and leads to complete infertility and hypogonadism." (PMID 28164172, 2016). "The absence of VAX1 in GnRH neurons results in infertility and the absence of hypothalamic GnRH neurons, observed as early as late embryonic development." (PMID 27389022, 2016).
mood disorder (1 paper, 2023). A cognitive disorder a disturbance in which the person's mood is hypothesized to be the main underlying feature. "Taken together, these data point to a novel role of VAX1 in regulating VIP neuron modulation of mood and the reproductive axis and raise the potential of Vax1Vip females to serve as a new model for mood disorders that are tied to reproductive cycles, such as PMDD." (PMID 38205198, 2023).
prostate tumours (1 paper, 2009). "The genes with the greatest fold changes in the datasets, FOXC1 and VAX1, will require future validation in a larger series of prostate tumours." (PMID 19283074, 2009).
Septo-optic dysplasia (1 paper, 2012). Septooptic dysplasia (SOD) is a clinically heterogeneous disorder characterized by the classical triad of optic nerve hypoplasia, pituitary hormone abnormalities and midline brain defects. "Furthermore, we are able to confirm previous results that the Vax1 gene is involved in Septo-Optic Dysplasia and suggest Gdf6 and Marcks as further potential candidates." (PMID 22719993, 2012). "Furthermore, we are able to provide evidence that Vax1 (MGI:1277163) is involved in Septo-Optic Dysplasia (OMIM:#182230) and suggest Gdf6 (MGI:95689) and Marcks (MGI:96907) as novel candidates." (PMID 22719993, 2012).
cancer (1 paper, 2012). A tumor composed of atypical neoplastic, often pleomorphic cells that invade other tissues. "The remaining other 4 genes, VAX1 KCNV1, ECEL1 and TMEM26, were found in the present study to be hypermethylated in BC, but there were no any background record that provided mechanisms in the carcinogenesis and development of any cancer, let alone BC." (PMID 22529986, 2012).
tumor (1 paper, 2012). "In this study, we found that VAX1 and LMX1A methylation was highly associated with tumor recurrence, suggesting that methylated VAX1 and LMX1A may serve as useful biomarkers to predict BC recurrence." (PMID 22529986, 2012).
VAX1 also shares sentences with these, for which no sentence is quoted: Anophthalmia (1 paper); Coffin-Siris syndrome (1); endometriosis (1); glaucoma (1); Leber congenital amaurosis 11 (1); lung carcinoma (1); microcephalic osteodysplastic primordial dwarfism type II (1); Peters anomaly (1); progressive myoclonic epilepsy-10 (1); retinal dystrophies (1); ventricular septal defect 2 (1).